LILRB2 (leukocyte immunoglobulin like receptor B2)
Diseases named in the same sentence as LILRB2 in open-access papers (continued):
Sharing a sentence is not in itself a finding about the gene and the disease.
infection (9 papers, 2009 to 2025). The state of being infected such as from the introduction of a foreign agent such as serum, vaccine, antigenic substance or organism. "In this context, we investigated the dynamics of the LILRB2/MHC-I inhibitory axis in DCs during the different phases of the infection." (PMID 35804458, 2022). "Dr Favier presented the dynamics of the LILRB2/MHC-I inhibitory axis in DCs during different phases of the infection." (PMID 35804391, 2022). "Infection with Salmonella typhimurium or TLR stimulation with Salmonella components led to an upregulation of LILRB2 and LILRB4." (PMID 19860908, 2009). "Interestingly, our results demonstrated that interaction scores of some paired ligands and receptors (e.g., ANXA1_FPR1, CD74_APP, CD74_COPA, CXCL1_CXCR1, CXCL2_CXCR2, and HLA-F_LILRB2) were significantly increased after infection." (PMID 37087411, 2023). "Indeed, given their strong capacity to attenuate immune response, LILRB1 and LILRB2 represent potential targets for pathogens to evade immune recognition, thereby extending the duration of infection." (PMID 35911674, 2022). "Moreover, levels of LILRB1 and LILRB2 expression were higher during symptomatic attacks than during asymptomatic infections." (PMID 35911674, 2022). "Infection of macrophages with Salmonella resulted in an upregulation of LILRB2 and LILRB4." (PMID 19860908, 2009). "We then used a macaque model of SIV infection to better characterize the dynamics of LILRB2 and MHC-I in the early phase of infection in blood and tissues." (PMID 35804458, 2022). "The dynamics of LILRB2 and MHC-I in the early phase of infection in blood and tissues was further characterized in a macaque model of SIV infection." (PMID 35804391, 2022). "To investigate the biology of LILRB2 and LILRB4 on antigen presenting cells in the context of infection, we infected monocyte-derived macrophages with Salmonella typhimurium transformed with the pFVP25.1-GFP plasmid." (PMID 19860908, 2009). "The ability of LILRB2 and LILRB4 to modulate T cell responses could also be of relevance during infection, where skewing of LILRB4 and/or LILRB2 expression might alter the course of an immune response." (PMID 19860908, 2009). "Our finding that LILRB2 and LILRB4 are upregulated in response to Salmonella stimulation indicates that these receptors play a role in limiting the inflammatory response during infection." (PMID 19860908, 2009). "Notably, the inhibitory receptors LILRB1 and LILRB2, which restrain antigen presentation and inflammatory signaling, were upregulated in response to HCMV, with LILRB2 being more prominently induced following TB40 infection." (PMID 40980889, 2025).
infectious disease (3 papers, 2009 to 2024). A disorder directly resulting from the presence and activity of a microbial, viral, or parasitic agent in humans. "Finally, LILRB1, LILRB2, and Tim3 expressions were evaluated as key inhibitory receptors implicated in the balance between parasite immune evasion and immune responses to infectious diseases." (PMID 38835780, 2024). "The differing roles of LILRB2 and LILRB4 on antigen presenting cell biology and in T cell/antigen presenting cell interactions warrant future studies that should prove useful in multiple fields of immunology and infectious disease." (PMID 19860908, 2009).
immune disease (2 papers, 2016 to 2019). "Of interest, deletion polymorphism encompassing the large part of LILRA3, a soluble receptor which possibly antagonizes binding of sHLA-G and LILRB1/LILRB2, has been associated with a variety of immune system disorders." (PMID 27331404, 2016). "Therefore, altered LILRB2 could be a contributing factor to auto-immune disease." (PMID 31671645, 2019).
bacterial infection (1 paper, 2009). "In addition to the high level expression that can render antigen presenting cells tolerogenic, there may be a role for lower level expression and activity of LILRB2 and LILRB4 in response to TLR signalling during an immune response to bacterial infection." (PMID 19860908, 2009).
neurodegenerative disease (1 paper, 2024). A disorder of the central nervous system characterized by gradual and progressive loss of neural tissue and neurologic function. "Moreover, transcriptome of DOLs in various neurodegenerative diseases, including AD, is characterized by increased expression of MHC-I, β2M, and complement component C4 (see the next paragraph); these are all genes coding for ligands of LILRB2/PIRB." (PMID 38299364, 2024).
LILRB2 also shares sentences with these, for which no sentence is quoted: gastric cancer (3 papers); acne (2); acquired immune deficiency syndrome (2); cutaneous melanoma (2); melanoma (2); ovarian carcinoma (2); preeclampsia (2); renal fibrosis (2); adenocarcinoma (1); age (1); angina (1); asthma (1); autoimmune disease (1); cardiovascular disease (1); cervical cancer (1); colon cancers (1); coronary artery disease (1); giant cell arteritis (1); glioblastoma (1); head and neck cancer (1); head and neck squamous cell carcinoma (1); Hepatic steatosis (1); juvenile idiopathic arthritis (1); kidney (1); kidney tumor (1); late-onset Alzheimers disease (1); Lewis lung carcinoma (1); lichen planus (1); lobular breast carcinomas (1); lung squamous cell carcinoma (1).
A further 9 diseases each share a sentence with LILRB2 in 1 paper.